FGF9 (fibroblast growth factor 9)
Description:
Plays an important role in the regulation of embryonic development, cell proliferation, cell differentiation and cell migration. May have a role in glial cell growth and differentiation during development, gliosis during repair and regeneration of brain tissue after damage, differentiation and survival of neuronal cells, and growth stimulation of glial tumors.
Synonyms: FGF-9; GAF; HBGF-9; HBFG-9; SYNS3
Tractability: Small molecule: it has a binding pocket of medium quality. Antibody: its Gene Ontology location is reachable by antibodies, with high confidence; UniProt places it where antibodies can reach, with medium confidence.
Gene: Protein-coding gene on chromosome 13 (21,671,073 to 21,704,498, forward strand). Ensembl gene ENSG00000102678.
Subcellular location: Secreted
Pathways (Reactome):
Signal Transduction: Downstream signaling of activated FGFR1; FGFR1c ligand binding and activation; FGFR2c ligand binding and activation; FGFR3b ligand binding and activation; FGFR3c ligand binding and activation; FGFR4 ligand binding and activation; FRS-mediated FGFR1 signaling; FRS-mediated FGFR2 signaling; FRS-mediated FGFR3 signaling; FRS-mediated FGFR4 signaling; Negative regulation of FGFR1 signaling; Negative regulation of FGFR2 signaling; Negative regulation of FGFR3 signaling; Negative regulation of FGFR4 signaling; PI-3K cascade:FGFR1; PI-3K cascade:FGFR2; PI-3K cascade:FGFR3; PI-3K cascade:FGFR4; PI3K Cascade; PI5P, PP2A and IER3 Regulate PI3K/AKT Signaling; PIP3 activates AKT signaling; Phospholipase C-mediated cascade: FGFR1; Phospholipase C-mediated cascade; FGFR2; Phospholipase C-mediated cascade; FGFR3; Phospholipase C-mediated cascade; FGFR4; RAF/MAP kinase cascade; SHC-mediated cascade:FGFR1; SHC-mediated cascade:FGFR2; SHC-mediated cascade:FGFR3; SHC-mediated cascade:FGFR4
Disease: Activated point mutants of FGFR2; Constitutive Signaling by Aberrant PI3K in Cancer; Signaling by FGFR1 in disease; Signaling by FGFR2 in disease; Signaling by FGFR3 in disease; Signaling by activated point mutants of FGFR1; Signaling by activated point mutants of FGFR3
Developmental Biology: Transcriptional regulation of testis differentiation
Gene Ontology:
Molecular function: fibroblast growth factor receptor binding; growth factor activity
Biological process: fibroblast growth factor receptor signaling pathway; male gonad development; positive regulation of cell population proliferation; positive regulation of vascular associated smooth muscle cell proliferation; substantia nigra development; cell-cell signaling; negative regulation of vascular associated smooth muscle cell differentiation; neurogenesis; positive regulation of MAPK cascade; positive regulation of vascular associated smooth muscle cell migration; regulation of cell migration; signal transduction; eye development
Cellular component: extracellular region; cytoplasm
Genetic constraint (gnomAD): Loss-of-function variants: 3 observed, 18.57 expected, observed/expected ratio (o/e) 0.16, 90% interval 0.073 to 0.42. The upper end of that interval is the gene's LOEUF score, 0.42, which puts it in group 1 of 6, group 1 being the genes least tolerant of losing a copy. Missense variants: 173 observed, 269.57 expected, observed/expected ratio (o/e) 0.64, 90% interval 0.57 to 0.73. Synonymous variants: 105 observed, 112.19 expected, observed/expected ratio (o/e) 0.94, 90% interval 0.8 to 1.1.
Gene-disease validity (ClinGen):
ClinGen rates the evidence that FGF9 causes each of these diseases.
multiple synostoses syndrome (autosomal dominant): Definitive. Multiple synostoses syndrome (MSS) is a rare developmental bone disorder characterized by proximal symphalangism of the fingers and/or toes often associated with fusion of carpal and tarsal, humeroradial, and cervical spine joints.
Homologues: Orthologues: chimpanzee FGF9 (100% identical), dog FGF9 (100% identical), macaque FGF9 (100% identical), rabbit FGF9 (100% identical), mouse Fgf9 (99% identical), pig FGF9 (99% identical), tropical clawed frog fgf9 (94% identical), rat Fgf9 (64% identical). Paralogues in human: FGF20 (71% identical), FGF16 (70% identical), FGF5 (33% identical), FGF3 (33% identical), FGF10 (32% identical), FGF13 (31% identical), FGF6 (31% identical), FGF11 (30% identical), FGF22 (30% identical), FGF4 (30% identical), FGF7 (30% identical), FGF14 (29% identical), and 9 more.
Diseases named in the same sentence as FGF9 in open-access papers:
FGF9 is named in the same sentence as 146 diseases in open-access papers, as found by Europe PMC text mining. Sharing a sentence is not in itself a finding about the gene and the disease. The quoted sentences say what the papers report.
gastric cancer (34 papers, 2013 to 2026). A primary or metastatic malignant neoplasm involving the stomach. "The combination of FGF9 expression alongside other genes can inhibit gastric cancer cells proliferation and is an independent risk factor for predicting gastric cancer patient survival." (PMID 34425560, 2021). "Taken together, our data suggest that FGF9 is a possible mediator secreted from cancer-associated fibroblasts that promotes the anti-apoptosis and invasive capability of gastric cancer cells." (PMID 25925261, 2015). "Another study on gastric cancer showed that miRNA-214-5p inhibited the tumor enhancement effect of tumor-associated fibroblast on gastric cancer by targeting fibroblast growth factor 9 (FGF9) in tumor-associated fibroblast and regulating epithelial to mesenchymal transition in gastric cancer." (PMID 34863188, 2021). "FGF-9 promotes the anti-apoptotic and invasive capability of gastric cancer cells, whereas upregulated miR-106b is associated with poor patient prognosis, as it enhances gastric cancer cell migration and invasion." (PMID 30813438, 2019). "A previous study identified the lncRNA-miRNA-mRNA axis involving LINC01140, miR-140-5p, and FGF9, which regulates gastric cancer phenotypes and impacts cell aggressiveness." (PMID 40696350, 2025). "The overexpression of FGF9 is closely related to the occurrence of gastric cancer and bladder cancer." (PMID 41155018, 2025). "In gastric cancer, downregulation of miR-214 in CAFs resulted in a high expression of Fibroblast Growth Factor 9 (FGF9), promoting EMT and tumor metastasis." (PMID 36185262, 2022). "The knockdown of FGF9 in gastric cancer cell lines induced apoptosis, while the high expression of FGF9 in gastric cancers was correlated with a poor prognosis." (PMID 34360000, 2021). "Comparison of normal gastric epithelial cells and tissues vs. gastric cancer cell lines and tumors, and is miR-486-5p is a combinatorial risk factor alongside olfactomedin-4 (OLFM4) and fibroblast growth factor 9 (FGF9)." (PMID 34425560, 2021). "In gastric cancer, the abnormal expression of FGF9 in lymph node CAFs was correlated with poor prognosis." (PMID 34745945, 2021). "For instance, miR-26a can suppress the proliferative ability and metastasis of gastric carcinoma by modulating FGF9." (PMID 34511023, 2021). "CAFs stimulate EMT in gastric cancer cells in a microRNA-214-dependent manner—it induces tumor-promoting ability of CAFs through fibroblast growth factor 9 (FGF9) targeting." (PMID 32340207, 2020). "In gastric cancer, miR-26a also seems to act as a tumor suppressor, bytargeting fibroblast growth factor 9 (FGF9) and inhibiting cell proliferation andmetastasis." (PMID 27508057, 2016). "DAPI staining and flow cytometry analysis showed that knockdown of FGF9 induced apoptosis in gastric cancer cells compared with controls." (PMID 27166269, 2016). "Cell growth and colony formation experiments showed that knockdown of FGF9 inhibited cell growth in both gastric cancer cell lines compared with control siRNA transfections (P<0.01)." (PMID 27166269, 2016). "Although it is unclear how FGF9 promotes the invasion of gastric cancer cells, degradation of the extracellular matrix is an important part of this process." (PMID 25925261, 2015). "In vitro studies demonstrated that FGF9 treatment increased the number of invading gastric cancer cells, whereas this increased invasive ability was suppressed by adding FGF9 neutralizing antibody." (PMID 25925261, 2015). "Since FGF9 serves as mitogen for prostate or ovarian cancer, we first investigated the proliferation of gastric cancer cells in the presence of FGF9 in vitro." (PMID 25925261, 2015). "We examined the effect of FGF9 on proliferation, invasion and anti-apoptosis of gastric cancer cells, and moreover clarified the intracellular signaling by which FGF9 exerts its biological effects on gastric cancer cells." (PMID 25925261, 2015).
gastric cancer (continued). "FGF9 is a possible mediator secreted by CAFs that promotes the anti-apoptosis and invasive capability of gastric cancer cells." (PMID 25925261, 2015). "On the other hand, we clarified in the present study that FGF9 has an anti-apoptotic effect on gastric cancer cells, in accord with the findings of several previous studies." (PMID 25925261, 2015). "In summary, we have shown that gastric CAFs differ from their corresponding NGFs in terms of their gene expression profiles, and propose that FGF9 is a potential molecule that mediates cross-talk between CAFs and gastric cancer cells." (PMID 25925261, 2015). "Since FGF9 is known to have a mitogenic effect on some cell types, we first tested the effect of FGF9 on the growth kinetics of gastric cancer cells." (PMID 25925261, 2015). "Additionally, downregulation of miRNA‐214 in gastric cancer results in increased FGF9 expression, thereby promoting the EMT process in gastric cancer cells, ultimately enhancing their migration and invasion abilities in vitro." (PMID 40977522, 2025). "The derivative short peptide P4, which is highly homologous to the extracellular domain of FGFR3c, can inhibit the proliferation, migration and invasion of tumor cells induced by FGF9, and can increase the sensitivity of gastric cancer cells to chemotherapy drugs." (PMID 41155018, 2025). "The analysis has conveyed that overexpression of FGF9 could provide a new clinical strategy in gastric cancer and bladder cancer." (PMID 35190498, 2022). "miR-214 was found to target fibroblast growth factor 9 (FGF9) in gastric cancer cells, and an experiment showed that it prevented cell fibrosis, increased the expression of E-cadherin, and decreased the expression of vimentin and N-cadherin to negatively regulate EMT." (PMID 35805066, 2022). "FGF9 is identified as an important epithelial-to-mesenchymal transition signal required for embryo development, furthermore, it has been reported to be expressed in various tumors, such as colon cancer, gastric carcinoma and lung carcinoma." (PMID 33234721, 2020). "We then examined the biological effects of FGF9 during progression of gastric cancer." (PMID 25925261, 2015). "In the present study, we showed that CAFs are a possible source of FGF9, and that furthermore gastric cancer cells have receptors that are responsive to FGF9, suggesting that FGF9 may be a potential mediator between CAFs and gastric cancer cells." (PMID 25925261, 2015). "To further identify the possible role of FGF9 in tumor progression, we examined whether exogenous FGF9 confers an anti-apoptotic effect on gastric cancer cells." (PMID 25925261, 2015). "Moreover, we confirmed that FGF9 is strongly expressed in the fibroblasts in the stroma of the gastric cancer lesion from which CAF was isolated." (PMID 25925261, 2015). "Here we performed microarray analyses to compare gene expression profiles between CAFs and non-cancerous gastric fibroblasts (NGFs) from a patient with gastric cancer and found that fibroblast growth factor 9 (FGF9) was a novel growth factor overexpressed in CAFs." (PMID 25925261, 2015). "As a major stromal population, “activated” fibroblasts, referred to as CAFs, have been suggested to promote tumorigenesis using various molecular signals, and in the present study we isolated FGF9 as a novel gene that was overexpressed in CAFs in gastric cancer." (PMID 25925261, 2015). "What is the possible role of FGF9 in the pathogenesis of gastric cancer?" (PMID 25925261, 2015). "Of the 20 gastric cancer tissue samples examined, sixteen (80%) was positive for FGF9 expression." (PMID 25925261, 2015). "There is suggestive evidence that miR-214 can regulate the expression of FGF9, impeding the migration and invasion of gastric cancer (GC) cells." (PMID 38817897, 2024).
gastric cancer (continued). "In recent years, researchers have increasingly recognized the important role of FGF9 in the development of several types of cancers, such as breast cancer, ovarian cancer, gastric cancer and colon cancer, however, it is still obscure whether FGF9 participates the NASH driven HCC." (PMID 37566761, 2023). "We also examined whether FGF9 promotes the invasive ability of gastric cancer cells." (PMID 25925261, 2015). "Moreover, we next examined the effect of FGF9 on the invasive ability of gastric cancer cells." (PMID 25925261, 2015). "Thus, like other FGF family proteins, FGF9 may play a pivotal role in the interaction between cancer cells and their surrounding stromal cells, and it is noteworthy that FGF9 is strongly expressed in CAFs in gastric cancer." (PMID 25925261, 2015). "CAF-derived low-expressed miR-214 removes the inhibition on FGF9 and EMT of gastric cancer cells, then enhances the capacities of migration and invasion of gastric cancer cells by means of decreasing E-cadherin and increasing N-cadherin and Snail expression." (PMID 34202583, 2021). "We investigated the effect of FGF9 stimulation on possible pathways including ERK and Akt in gastric cancer cell lines." (PMID 25925261, 2015). "The effects of FGF9 on AGS and MKN28 gastric cancer cells in terms of proliferation, invasion and anti-apoptosis were assessed by WST-1 assay, invasion chamber assay and FACS, respectively." (PMID 25925261, 2015). "Moreover, we examined the effect of anti-FGF9 neutralizing antibody on gastric cancer cells and found that the increased expression of p-Akt and p-ERK elicited by FGF9 stimulation was attenuated by concomitant administration of anti-FGF9 neutralizing antibody." (PMID 25925261, 2015). "Among these genes, we targeted FGF9 as the most highly expressed gene to examine the role of this CAF-produced growth factor on gastric cancer cells, and in fact before starting in vitro studies we confirmed that CAF cells produced much larger amount of FGF9 protein than NGF cells." (PMID 25925261, 2015).
hepatocellular carcinoma (20 papers, 2013 to 2025). A malignant tumor that arises from hepatocytes. "FGF9 has been shown to be implicated in cancers, such as ovarian endometrioid adenocarcinoma, hepatocellular carcinoma, and prostate carcinoma." (PMID 30227870, 2018). "FGF9 has been shown to be implicated in different cancers such as ovarian endometrioid adenocarcinoma, hepatocellular carcinoma and prostate carcinoma." (PMID 24015269, 2013). "Overall, these data show that FGF9 acts as a potent growth factor for hepatoma/hepatocarcinoma cells and appears to enhance the cells ́ ability for clone formation, migration and disintegration of blood/lymphatic endothelia." (PMID 32378800, 2020). "Under these experimental conditions FGF9 enhanced the invasive phenotype of all hepatoma/hepatocarcinoma cell lines by enhancing the disintegration of the endothelium by the spheroids." (PMID 32378800, 2020). "Any of the FGF9 effects in hepatoma/hepatocarcinoma cells was blocked completely by applying the FGFR1‐3‐specific tyrosine kinase inhibitor BGJ398 or siFGFR3, while siFGFR1/2/4 were mostly ineffective." (PMID 32378800, 2020). "This was first and indirect evidence that in the hepatoma/hepatocarcinoma cells FGF9 acts largely via FGFR3‐IIIb/IIIc." (PMID 32378800, 2020). "FGF9 was found to be the most potent growth stimulator of the hepatoma/hepatocarcinoma cells and to enhance also the invasive/migratory phenotype of the cells." (PMID 32378800, 2020). "FGF9 is a well-known oncogenic gene in human cancers including ovarian cancer, hepatocellular carcinoma, NSCLC and other cancers." (PMID 31884893, 2020). "This was strong evidence that FGF9 is a driver of the aggressive phenotype of hepatoma/hepatocarcinoma cells, mediated via FGFR3‐IIIb and/or FGFR3‐IIIc." (PMID 32378800, 2020). "FGF9 enhanced significantly the clone‐forming capacity of all hepatoma/hepatocarcinoma lines except for HepG2 cells." (PMID 32378800, 2020). "In fact, high FGF9 expression is found in various human tumors such as prostate cancer, non small-cell lung cancer, hepatocellular carcinoma and ovarian endometrioid adenocarcinom, and is significantly associated with the progression of these cancer cells." (PMID 32366371, 2020). "Among all FGFR3‐IIIb/IIIc ligands tested, FGF9 was the most potent growth factor for hepatoma/hepatocarcinoma cells." (PMID 32378800, 2020). "In hepatoma/hepatocarcinoma cells FGF9 enhanced the capability for clonogenicity and disintegration of the blood and lymphatic endothelium, being most pronounced in cells overexpressing FGFR3‐IIIb or FGFR3‐IIIc, respectively." (PMID 32378800, 2020). "Our data also show that metabolic stress such as palmitate induces FGF9 expression in activated fibroblasts, thereby increasing cell migration and viability in fibroblasts and hepatoma cells in vitro, and thus promoting tumor growth in vivo." (PMID 31862949, 2019). "FGF9 exerted anti-apoptotic and pro-migratory effects in fibroblasts and hepatoma cells in vitro and accelerated tumor growth in a subcutaneous xenograft model." (PMID 31862949, 2019). "FGF9 has been shown to be dysregulated in ovarian endometrioid adenocarcinoma, hepatocellular carcinoma, prostate carcinoma and GC." (PMID 27166269, 2016). "So far, the direct validated targets of this miRNA include stem cell self-renewal regulator SOX2 in breast cancer, TGFBR1 and FGF9 in hepatocellular carcinoma, SOX9 and ALDH1 in ductal carcinoma in situ and IGF1R in lung cancer." (PMID 26882564, 2016). "In hepatocellular carcinoma, miR-140 functions as a tumor suppressor, where it directly suppresses Fgf9 expression." (PMID 25978641, 2015). "A pre-clinical study suggested that βKlotho mediates FGF9 pro-survival functions in hepatocellular carcinoma via FGFR3 and FGFR4 and may be useful in selecting patients who could benefit from anti-FGFR therapies." (PMID 37958253, 2023).